BECN1 (beclin 1)
Diseases named in the same sentence as BECN1 in open-access papers (continued):
Sharing a sentence is not in itself a finding about the gene and the disease.
breast carcinoma (continued). "In addition, previous studies have shown that ErbB2 can block autophagy initiation by modulation of Beclin 1 in breast cancer and Alzheimer’s disease, and regulate autophagic cell death by modulation of ATG4B expression in retinal pigment epithelium cells." (PMID 33854045, 2021). "From this analysis of the role of the TFEB pathway in breast cancer chemoresistance, we reveal evidence that the increased expressions of TFEB and Beclin-1 are associated with a shorter survival period in patients suffering from invasive breast cancer who undergo chemotherapy." (PMID 34663249, 2021). "Furthermore, Liu and coworkers found an increased expression of Beclin-1 in the tamoxifen-resistant breast cancer cell line." (PMID 34663249, 2021). "Increased Beclin-1 expression was noted in tamoxifen-resistant breast cancer cell line." (PMID 34490076, 2021). "In addition, Becn1+/+ mice displayed decreased tumorigenesis compared with Becn1+/− mice in a Proto-Oncogene WNT1 (WNT1)-driven breast cancer model as well as in spontaneous breast cancer formation following parity." (PMID 34207792, 2021). "Further studies may reveal Bag-1/Beclin 1 complex as a targetable component of autophagic progress in breast carcinomas." (PMID 33561998, 2021). "Beclin-1 (BECN1) has been identified as a tumor suppressor that participates in the lysosomal degradation pathway to enhance autophagy and it is expressed at lower levels in mammary carcinomas, particularly TNBC." (PMID 32296646, 2020). "Likewise, co-treatment with BEZ235 and Trichostatin A enhanced autophagic cell death via up-regulating LC3B-II and Beclin-1 expression, finally exerting anti-tumor activity in breast cancer." (PMID 32716025, 2020). "Beclin 1 loss is associated with poor patient survival and more aggressive cancers and mouse models harboring a single Beclin 1 copy have elevated incidence of spontaneous malignancies, including lung carcinomas, lymphomas, hepatocellular carcinomas and breast carcinomas." (PMID 33287140, 2020). "However, breast carcinoma cells knocked down for BECN1 show decreased tumor growth in vivo, indicating that in developed carcinoma cells, BECN1 behaves as an oncogene." (PMID 33363032, 2020). "Although curcumin can impair the autophagic flux (discussed in Section 4), the association of curcumin and berberine in breast cancer cells MCF-7 and MDA-MB-231 stimulates cell death mediated by autophagy by positive regulation of beclin-1 and phosphorylation of JNK." (PMID 33233671, 2020). "Furthermore, low BECN1 mRNA expression was associated with HER2 amplification and a much poorer disease-specific survival in HER2+ breast cancer." (PMID 33287140, 2020). "Furthermore, BECN1 overexpression in MCF7 breast carcinoma cells reduced tumorigenesis in nude mice." (PMID 33224954, 2020). "Indeed, after 24 h of treatment, EPADA and DHADA increase beclin-1 transcriptional activity in breast cancer cells, activating the autophagic flux." (PMID 33352766, 2020). "A decreased gene expression level of Beclin-1 has been noted in many breast cancer cells." (PMID 32466337, 2020). "However, at the same time, CBD increased the level of beclin-1, favouring autophagosome formation, which has previously been shown only in breast cancer cells." (PMID 31466340, 2019). "Downregulation of the important autophagic proteins ULK and Beclin-1 often occurs in breast cancer, particularly in TNBC, suggesting that activation of autophagy may be beneficial." (PMID 31921382, 2019). "In breast cancer, BECN1 was required for tumorigenicity of cancer stem cells." (PMID 31272261, 2019). "Heterozygous Beclin 1 (beclin 1+/- mutant) was shown to have a high incidence of spontaneous tumors, whilst Beclin 1 inhibited tumor growth in cell lines such as the breast cancer cell line, MCF-7, in which Beclin 1 expression was lower than in normal epithelial breast cells." (PMID 31277291, 2019). "Genetically inhibition of BECN1 blocked tumor formation in mammary cancer stem cells." (PMID 31272261, 2019).
breast carcinoma (continued). "Besides, Bax activated apoptosis which led to the type I programmed death of breast cancer cells while Beclin 1 initiated the excessive autophagy that resulted in the type II programmed death of breast cancer cells." (PMID 30304783, 2018). "Beclin-1 is aberrantly expressed in breast cancer and has been suggested as a therapeutic target." (PMID 29300316, 2018). "Study reported that overexpressed Beclin-1 may promote autophagy in autophagy-defective breast cancer cells." (PMID 29300316, 2018). "Beclin1 is a mammalian autophagy-related protein, key in the initiation and nucleation processes; beclin-1 gene is monoallelically deleted in 40–75% of breast, ovarian and prostate cancers and has reduced expression in human breast carcinoma lines." (PMID 30182146, 2018). "These deletions are generally extensive and affect BRCA1 along with several other genes, including BECN1, suggesting that the deletion of BRCA1, not the deletion of BECN1, is the driver mutation in breast cancer." (PMID 30540126, 2018). "Also, Beclin-1 is allelically deleted and weakly expressed in most human breast carcinoma cell lines while the normal epithelium cells demonstrated a much higher expression." (PMID 28320471, 2017). "In addition, our results suggested that overexpression of HER2 in Beclin 1 knockdown breast cancer cells can restore TAM resistance." (PMID 28881721, 2017). "In this study, we first determined whether the change of interaction between Bcl-2 and Beclin 1 was responsible for the formation of protective autophagy in the established TAM-resistant breast cancer cells." (PMID 28431397, 2017). "Previously Beclin 1 has been known as a haplo-insufficient tumor suppressor which might be monoallelically deleted or decreased in many cancers, such as breast cancer." (PMID 28881721, 2017). "Furthermore, in the presence of tamoxifen, inhibited pAkt and pERK1/2 protein of Beclin 1 knockdown breast cancer cells were reactivated after HER2 overexpression in our western blot results." (PMID 28881721, 2017). "To test our hypothesis that it is autophagy that protects ER+ breast cancer cells from palbociclib-induced senescence at low doses, we first downregulated two crucial autophagy genes, Beclin-1 and Atg-5 (refs 29, 30)." (PMID 28653662, 2017). "The role of Beclin 1 in breast cancer exists different opinions." (PMID 28881721, 2017). "Their data suggested that the HER2-Beclin 1 complex is present at the cell surface of HER2-expressing breast cancer cells and this complex is disrupted by lapatinib treatment, which concomitantly induces adaptive autophagy in lapatinib-resistant breast cancer cells." (PMID 27556700, 2016). "Furthermore, EHMT2 showed a reciprocal expression pattern with Beclin-1 in The Cancer Genome Atlas (TCGA) of breast cancer patients." (PMID 27174920, 2016). "In line with the results of these studies, lower LC3 or beclin-1 protein expression has also been found in cancer cells than in adjacent normal tissues in various human malignancies, including ovarian cancers, breast cancers, and esophageal cancers." (PMID 26965179, 2016). "For example, beclin-1-transfected breast cancer cells have lower sensitivity to the proliferative effects of the estrogen receptor agonist E2 and the growth-suppressive effects of tamoxifen, contributing to acquisition of resistance with a concomitant increase in autophagy." (PMID 27863404, 2016). "Therefore, we assessed the relationship between the expression of EHMT2 and Beclin-1 and the survival rate of breast cancer patients from two large datasets, the Netherlands Cancer Institute (NKI) and University of North Carolina (UNC) cohorts." (PMID 27174920, 2016). "Beclin 1 appears to be required for maintenance of a cancer stem cell population in breast cancers." (PMID 27655644, 2016).
breast carcinoma (continued). "Notably, although beclin-1 is normally expressed in the ductal epithelial cells of mammary glands, many breast cancer cells lack beclin-1 expression due to a combination of monoallelic deletion and epigenetic silencing of the beclin-1 gene." (PMID 25955408, 2015). "Nonetheless, since the majority of breast cancer cases with BRCA1 or BECN1 copy number alteration contain concurrent deletions of both BRCA1 and BECN1, it is difficult to use copy number alterations as a parameter for distinguishing the effects of these two genes in breast cancer." (PMID 25825707, 2015). "Therefore, we sought to determine the importance of loss of BECN1 and of BRCA1 expression in women with ER-negative subtypes of breast cancer." (PMID 25825707, 2015). "Despite these findings, which highlight the important role of beclin-1 expression in the cancer-stromal niche, the combined effects of beclin-1 expression in tumor and stromal cells on prognosis of breast cancer patients remain unclear." (PMID 25955408, 2015). "Taken together, our findings suggest that decreased BECN1 expression may contribute to the pathogenesis and/or progression of certain breast cancers, especially the ER-negative subtypes." (PMID 25825707, 2015). "However, beclin-1-dependent autophagy is required for the tumorigenicity of breast cancer stem-like/progenitor cells." (PMID 25955408, 2015). "Taken together, these findings indicate beclin-1 expression in the stroma might be important for shaping the breast cancer microenvironment and thus could be a potent molecular target in patients with invasive ductal carcinoma of the breast." (PMID 25955408, 2015). "Notably, siRNA-mediated downregulation of beclin-1 in mesenchymal cells co-cultured with breast cancer cells decreased the levels of various pro-inflammatory cytokines, their receptors, and collagen receptors." (PMID 25955408, 2015). "In this study, we first asked whether beclin-1 expression in invasive ductal carcinoma cells and/or stromal cells correlated with the prognosis of breast cancer patients." (PMID 25955408, 2015). "Many breast carcinoma cell lines, although polyploidal for chromosome 17 (BECN1 gene is placed in 17q21 loci), exhibit deletions of one or more BECN1 alleles, and human breast tumors show decreased Beclin-1 levels compared to normal adjacent tissue." (PMID 25317422, 2014). "However, Beclin 1 expression is downregulated in other malignancies, such as breast cancer and esophageal squamous cell carcinoma, suggesting different roles for Beclin 1 in different cancers." (PMID 24675697, 2014). "Notably, SKBR3 and MCF7-GFPLC3 cells contain monoallelic deletions of a tumor suppressor gene BECN1, a prominent regulator of early phagosome formation, observed in ~40% of human sporadic breast cancers." (PMID 24146879, 2013). "A decreased expression of BECN1 has been identified in human breast carcinoma, and BECN1 has been suggested to be a mammalian autophagy gene that may inhibit tumorigenesis." (PMID 23833647, 2013). "For instance, tumorigenesis is suppressed by Beclin 1 expression in human MCF7 breast cancer cells." (PMID 23840208, 2013). "Under the nutrient-deprived stress, mesenchymal stem cells (MSCs) survived by activating Beclin 1 mediated autophagy, and facilitated breast cancer MCF-7 cells to invasiveness through upregulating histone deacetylases 6 (HDAC6) activity and increasing motility." (PMID 24303007, 2013). "In addition, transfection of MCF-7 breast cancer cells, that express low levels of Beclin 1, with BECN1 gene, inhibits growth and tumor formation." (PMID 22295229, 2011). "The results here provided some new insights into the regulation of beclin 1 in breast cancer." (PMID 20230646, 2010). "The findings here shed some new light on the regulatory mechanisms of beclin 1 in breast cancer." (PMID 20230646, 2010). "LOH at the beclin 1 locus was observed in 9 out 22 (41%) of the breast cancer cell lines." (PMID 20230646, 2010).
breast carcinoma (continued). "In MCF-7 and MDA-MB-231 breast cancer cells, artesunate was capable of inhibiting the proliferation of these cancer cells through inducing autophagy, which was indicated by up-regulation of Beclin-1 and aggregation of LC3-II and increasing sensitivity to the chemotherapy drug epirubicin." (PMID 39539439, 2024). "This could be attributed to the heightened autophagic activity in MDA-MB-231 and BT-549 cells following Beclin-1 gene transfection, providing a mechanism by which breast cancer cells reduce their metabolic stress and thus promote their survival in harsh environments such as starvation and hypoxia." (PMID 38315272, 2024). "However, as research advanced, a more complex picture emerged, demonstrating that Beclin-1 could promote breast cancer progression, even when highly expressed in some patients." (PMID 38315272, 2024). "It was found that in Beclin-1 gene-deficient breast cancer MDA-MB-231 cells could be detected, the phosphorylation levels of ERK and AKT were increased in breast cancer cells, Beclin-1 was negatively correlated with the intensity and duration of growth factor receptor signaling pathway persistence." (PMID 38315272, 2024). "Multiple in vitro investigations have demonstrated an upregulation of Beclin-1, ATG7, LC3-II, and p62 expression levels in malignancies associated with breast cancer (BC) and chronic myeloid leukemia (CML)." (PMID 38794148, 2024). "Additionally, GRP78 indirectly activates BECN1 to promote autophagy in breast cancer cell lines." (PMID 37190065, 2023). "A recent study demonstrated that carnosol (phenolic diterpene), a naturally occurring molecule, may arrest the cell cycle in the G2 phase and promote ROS-dependent apoptosis and beclin-1-independent autophagy in triple-negative MDA-MB-231 human breast cancer cells." (PMID 35408561, 2022). "In addition, treatment of HER2+ human breast cancer xenografts with the Tat-BECN1 autophagy-inducing peptide induced autophagy in vivo within the tumor, compromised the HER2/BECN1 interaction, induced a unique transcriptional profile and, most importantly, greatly inhibited tumor growth." (PMID 35832792, 2022). "Moreover, talazoparib treatment also enhanced red only (RFP+ GFP−) punctae (i.e., autophagolysosomes) and yellow (RFP+ GFP+) punctae (i.e., autophagosomes) formation in mRFP-EGFP-LC3 expressing BECN1-KO breast cancer cells similar to that seen in control MCF-7 cells." (PMID 33473172, 2021). "In addition, the in vivo administration of quercetin (50 mg/kg, intraperitoneally (i.p.), twice daily for a month) was able to reduce the size of the tumors and to reduce the level of the protein Beclin 1 and of phospho-Akt/Akt ratio in tumor tissues in a breast cancer xenograft mouse model." (PMID 32927836, 2020). "al., who first sequenced the BECN1 gene (which encodes the beclin-1/ATG6 protein), followed by the discovery that a BECN1 allele is often deleted in some types cancer and that beclin-1 induces autophagy and inhibits tumor formation in human breast cancer cell line MCF-7." (PMID 33233671, 2020). "However, for long-term exposure, DHADA and EPADA block autophagy inducing the cleavage of caspase-9 and beclin-1 and activate the apoptotic cascade, enhancing the cytochrome c release into the cytoplasm and the DNA fragmentation in different breast cancer cell lines." (PMID 33352766, 2020). "Similarly, silibinin is a flavonolignan, extracted from milk thistle (Silybum marianum), and has been reported to provoke autophagic cell death in breast cancer cells by downregulating the Bcl-2 expression and upregulation of Atg12-Atg5 formation and enhancing beclin-1 expression." (PMID 29681985, 2018).
breast carcinoma (continued). "In addition, overexpression of Beclin-1 in human breast carcinoma cell line MCF-7 cells could reduce tumourigenesis by inhibiting cell proliferation in a xenograft model." (PMID 28320471, 2017). "Herein, in the aim of further explore OHPg/PR-B protective effects in breast cancer we investigate how PR-B prolonged activation, driving autophagy through Beclin-1, may influence cell cycle control by intercepting a signalling pathway responsible for autophagy-senescence transition." (PMID 27462784, 2016). "Thus, the functional release of Bcl-2 from Beclin-1 interaction may represent the molecular bridge connecting autophagy to an irreversible G1 arrest, thus determining breast cancer cell fate decision." (PMID 27462784, 2016). "Moreover, levels of EHMT2 and Beclin-1 expression may represent useful prognostic markers for patients with breast cancer." (PMID 27174920, 2016). "Whereas the origin of the autophagy disruption is still unknown, mutations or loss of heterozygosity-dependent autophagy gene silencing (LC3, ATGs, UVRAG, BECN-1) have been reported in many different cancers, such as colorectal, gastric carcinoma or breast cancers." (PMID 26474850, 2015). "Interestingly we evidenced the appearance of an authophagic phenotype by Bg treatment as revealed by fluorescence microscopy of LC3-GFP in breast cancer cells together with an increase of different key hallmarks of the autophagic process such as Beclin 1, PI3K III, UVRAG and Ambra1." (PMID 26148846, 2015). "We propose that the decreased expression of BECN1 (another tumor suppressor gene located near BRCA1) in sporadic basal-like breast tumors may partly explain the phenotypic overlap of this disease with hereditary BRCA1 breast cancer." (PMID 25825707, 2015). "Beclin-1 mediates the cellular autophagy pathway, which is responsible for the degradation of the human epidermal growth factor 2 (HER2) in breast cancer and EGFR in NSCLC." (PMID 40243822, 2025). "Specifically, in breast cancer (BRCA) and head and neck squamous cell carcinoma (HNSC), PRKN, PINK1, and MAP1LC3A were downregulated, while SRC and BECN1 were upregulated." (PMID 39859167, 2025). "HOTAIR also acts as a competing endogenous RNA (ceRNA), sequestering miR‐34a, a tumor suppressor that targets ATG4B, Beclin‐1, and HMGB (high mobility group box) proteins, which is an anti‐autophagic miRNA in breast cancer." (PMID 41329030, 2025). "Beclin-1 is frequently monoallelically deleted in breast cancer and interacts with ATG14 to trigger apoptosis inhibition in breast cancer, leading to cancer progression and chemotherapy resistance." (PMID 40426890, 2025). "For example, in breast cancer (BRCA) we found that OPTN, PINK1 and PRKN expression was positively correlated with infiltration of NK cells, while that of BECN1 was negatively correlated with it." (PMID 39859167, 2025). "Our study demonstrates that miR-622 can modulate the expression levels of beclin 1-dependent genes, altering cancer progression and reinstating drug sensitivity by suppressing HIF-1α expression in breast cancer cells." (PMID 38339408, 2024). "In breast cancer and ovarian cancer, the E3 ligase cullin-3 (CUL3) interacts with BECN1, promoting its K48 ubiquitination and downregulating BECN1, ultimately enhancing tumor cell proliferation and resulting in a poor prognosis." (PMID 39048965, 2024). "We previously showed that BECN1 and HER2 interact in multiple HER2 overexpressing breast cancer cell lines and xenografts, and that HER2 overexpression inhibits autophagy." (PMID 38182563, 2024). "We demonstrated that the tested compound decreased Beclin-1 and LC3B concentrations in MCF-7 and MDA-MB-231 breast cancer cells." (PMID 39199694, 2024). "Doxorubicin increased the expression of the MAP1LC3B and BECN1 genes and elevated the concentrations of Beclin-1 and LC3B in the MCF-7 and MDA-MB-231 breast cancer cells." (PMID 39199694, 2024).